ROR2 (ROR family WNT receptor 2)
Diseases named in the same sentence as ROR2 in open-access papers (continued):
Sharing a sentence is not in itself a finding about the gene and the disease.
neuroblastoma (2 papers, 2022). Neuroblastoma (NB) is the most common solid, extracranial childhood tumor. "The RTK genes ROR1 and ROR2 were originally cloned form the neuroblastoma cell line SH-SY5Y." (PMID 34716856, 2022). "Additionally, as retinoic acid exerts its differentiation-stimulating effects through ROR2 and RORa in cultured mouse hippocampal neurons and neuroblastoma cell lines, we examined the roles of both RORa and ROR2 receptors in NME1-promoted neurite growth." (PMID 34623600, 2022). "Altogether, we found that RYK and ROR2, but not ROR1, are robustly associated with worse outcome in neuroblastoma." (PMID 34716856, 2022). "This is further supported by a recent study describing a role for ROR1, but not ROR2, in retinoic acid-induced neuroblastoma differentiation." (PMID 34716856, 2022). "Together, these data suggest that the WNT modifying pseudokinases ROR2 and RYK represent potential novel therapeutic targets for neuroblastoma treatment and that current research on immuno-therapeutic strategies against ROR1 might need to be re-evaluated in favor of ROR2 and RYK." (PMID 34716856, 2022). "Furthermore, ROR2 expression analysis in cancer cell lines (CCLE, Broad Institute) suggests a relatively high mRNA level in neuroblastoma cells, showing the highest average expression among all cancer cell lines, while ROR1 showing low specificity for neuroblastoma cell lines." (PMID 34716856, 2022).
ovarian tumor (2 papers, 2020 to 2022). "As ROR2 targeting approaches for other cancers are under development (including lung and ovarian tumors), our findings suggest that ALK+ ALCL cases with resistance to current therapies may also benefit from ROR2 targeting strategies." (PMID 35246138, 2022). "High level of Ror2 expression in platinum-resistant ovarian tumor was found to be coupled with upregulation of Stat3, suggesting that Stat3 might act as the signaling downstream of Ror2." (PMID 32216811, 2020). "In this regard, the current phase 1–2 trials of ADC antibody and CART targeting ROR2 for other tumor types (e.g., NSCLC and ovarian tumors: ClinicalTrials.gov #NCT03504488, NCT03960060, NCT03393936,) may also benefit ALK+ ALCL patients." (PMID 35246138, 2022).
triple-negative breast carcinoma (2 papers, 2021 to 2024). An invasive breast carcinoma which is negative for expression of estrogen receptor (ER), progesterone receptor (PR), and human epidermal growth factor receptor 2 (HER2). "Since some triple-negative breast cancers share the high-grade genomic instability observed in BRCA1/2-mutant cancers, the so-called BRCAness, we were interested in whether ROR2 could be linked to these changes." (PMID 34911552, 2021).
urothelial carcinoma (2 papers, 2021 to 2024). A malignant neoplasm derived from the transitional epithelium of the urinary tract (urinary bladder, ureter, urethra, or renal pelvis). "We investigated the association of receptor tyrosine kinase-like orphan receptor 2 (ROR2) expression with clinicopathological features and oncologic outcomes in large urothelial carcinoma (UC) of the upper tract (UTUC) and urinary bladder (UBUC) cohorts." (PMID 34440262, 2021). "We utilized a large dataset of urothelial carcinoma (UC) tumors to characterize non‐canonical WNT signaling through WNT5A, ROR1, ROR2, or FZD2 expression." (PMID 38558536, 2024). "The role of the WNT5A pathway (WNT5A, ROR1, ROR2, and FZD2) in the pathogenesis and progression of urothelial carcinoma (UC) has not been fully elucidated." (PMID 38558536, 2024).
Aarskog syndrome (1 paper, 2014). "The shawl scrotum and lax ligaments of Aarskog syndrome are not found in ROR2-related RS." (PMID 24932600, 2014).
adenoma (1 paper, 2016). A neoplasm arising from the epithelium. "Examination of ROR2 loss in a more adenoma like biological model instead of in cancer cell lines would also aide in determining if the silencing of the receptor promoted CRC progression." (PMID 27440078, 2016). "Our combined functional analysis indicates that ROR2 downregulation may cause increased proliferation and migration in early non-invasive adenomas, resulting in a more metastatic phenotype." (PMID 27440078, 2016). "Along with the methylation, there was also a corresponding loss of ROR2 expression in the adenoma samples, leading us to hypothesise that the observed downregulation was caused by epigenetic silencing through promoter hypermethylation." (PMID 27440078, 2016). "Additional analysis also revealed that adenoma samples with reduced ROR2 expression also possessed ROR2 promoter hypermethylation." (PMID 27440078, 2016). "qRT-PCR revealed 5 of the 6 adenomas had reduced ROR2 expression compared to matching normal mucosa samples." (PMID 27440078, 2016). "Our study has found that ROR2 promoter hypermethylation and subsequent expression loss is an early event in CRC progression that first occurs in non-invasive adenomas." (PMID 27440078, 2016). "Bisulphite sequencing showed that 4 of those adenomas were hypermethylated across the ROR2 CGI promoter." (PMID 27440078, 2016). "To determine whether hypermethylation of the ROR2 promoter was an early or late event in colorectal neoplasia, we compared the number of methylated samples in 88 non-invasive adenomas to 47 normal mucosa specimens." (PMID 27440078, 2016). "ROR2 expression was examined in CRC cell lines and patient adenomas using qRT-PCR, while COBRA and bisulphite sequencing was used to analyse ROR2 promoter methylation." (PMID 27440078, 2016). "ROR2 expression and methylation were examined in 6 adenoma samples chosen for their absence of submucosal infiltration and non-serrated histological profile." (PMID 27440078, 2016). "Using a mouse strain that had a high prevalence for adenomas such as the APC heterozygous 57BL/6 J-ApcMin/J mouse line, would allow for the determination of whether or not early ROR2 loss potentiates adenoma growth and development." (PMID 27440078, 2016).
Angelman syndrome (1 paper, 2016). A neurogenetic disorder characterized by severe intellectual deficit and distinct facial dysmorphic features. "Previous normal testing included chromosome analysis, FISH for 22q11 deletion, methylation studies for Prader Willi and Angelman syndromes, and ROR2 sequencing." (PMID 26739615, 2016).
Arthritis (1 paper, 2019). Inflammation of a joint. "The Wnt5a–Ror2 signalling pathway regulates the activity of chondrocytes, osteoblasts and osteoclasts and is overexpressed in arthritis tissues." (PMID 31313518, 2019).
B-cell acute lymphoblastic leukemia (1 paper, 2019). A neoplasm of lymphoblasts committed to the B-cell lineage, typically composed of small to medium-sized blast cells. "Moreover, other Wnt ligands have been shown to interact with either ROR1 or ROR2 in various cellular contexts, such as Wnt16–ROR1 interaction in TCF3-PBX1 B-cell acute lymphoblastic leukemia and Wnt9a–ROR2 interaction during skeletal development." (PMID 31382410, 2019).
bipolar disorder (1 paper, 2020). A disorder of the brain that causes unusual shifts in mood, energy, activity levels and the ability to carry out day-to-day tasks. "Moreover, the genes SPTLC1and ROR2 that were associated with YKL-40 level in serum are moderately associated with schizophrenia and bipolar disorder (P = 5.79 × 10−7) according to a previous GWAS49." (PMID 32066700, 2020).
bladder tumor (1 paper, 2021). "In Kaplan–Meier analysis, ROR2 high expression was associated with a high urinary bladder tumor recurrence rate (p < 0.0001)." (PMID 34440262, 2021). "In the multivariate analysis, we found that ROR2 expression status (HR: 3.033; 95% CI = 1.758–5.233, p < 0.001) and primary tumor stage and grade were independent predictors for urinary bladder tumor recurrence in patients with NMIBC." (PMID 34440262, 2021). "Patients with high ROR2 expression have three-times greater bladder tumor recurrence rate than those with low ROR2 expression, suggesting its prognostic role in NMIBC." (PMID 34440262, 2021).
bone sarcoma (1 paper, 2015). A sarcoma that arises from the bone. "LRP6, LRP8 and Ror2 levels were significantly higher in bone sarcoma cells than in hMSC, while LRP5 levels were decreased in bone sarcoma cells." (PMID 25999350, 2015).
breast tumors (1 paper, 2021). "We found ROR2 to be highly expressed in aggressive breast tumors and associated with worse metastasis-free survival." (PMID 34911552, 2021). "Correspondingly, a negative correlation between ROR2 and active canonical WNT signaling was revealed in human breast tumors based on the TCGA database." (PMID 34911552, 2021).
Burkitt lymphoma (1 paper, 2019). A rare form of malignant mature B-cell non-Hodgkin lymphoma. "Our results revealing highly phosphorylated EGFR, PDGFRβ, ROR2, ERK1/2, or Hsp27 in all samples are also in accordance with previously published findings on Burkitt lymphoma." (PMID 32117783, 2019).
cholangiocarcinoma (1 paper, 2020). A carcinoma that arises from the intrahepatic biliary tree (intrahepatic cholangiocarcinoma) or from the junction, or adjacent to the junction, of the right and left hepatic ducts (hilar cholangiocarcinoma). "The endocannabinoid AEA (10 μM) reduced the growth of cholangiocarcinoma in vivo model, upregulating Wnt5a expression with subsequent activation of receptor tyrosine kinase-like orphan receptor 2 (Ror2) and c-Jun N-terminal kinase JNK." (PMID 31979368, 2020).
chondrosarcoma (1 paper, 2017). A malignant cartilaginous matrix-producing mesenchymal neoplasm arising from the bone and soft tissue. "To test the Noggin-Ror2 synergy in a model system that is more relevant to skeletal development we decided to use the rat chondrosarcoma (RCS) cell line." (PMID 28523267, 2017).
clear cell renal cell carcinoma (1 paper, 2014). "Ror2 is a Wnt ligand receptor that is overexpressed in a variety of tumors including clear cell renal cell carcinoma (ccRCC)." (PMID 25542006, 2014).
colon adenocarcinoma (1 paper, 2010). "To determine whether ROR2 promoter hypermethylation is also a frequent in vivo event, we used methylation-specific PCR to analyse 36 primary colon adenocarcinomas." (PMID 20591152, 2010).
congenital heart disease (1 paper, 2023). A heart disease that is present at birth. "This strengthens our belief that ROR2 regulates HSPA6 expression through the β‐catenin/SOX3 signalling pathway, providing some clinical implications for treating TOF in congenital heart disease." (PMID 37749917, 2023).
cytomegalovirus infection (1 paper, 2020). A herpesvirus infection caused by Cytomegalovirus. "Cytomegalovirus infection also modulates the expression of noncanonical Wnt receptor tyrosine kinase-like orphan receptor 2 (ROR2) to alter Wnt5a-mediated signaling and inhibit trophoblast motility." (PMID 33374185, 2020).
glaucoma (1 paper, 2021). Increased pressure in the eyeball due to obstruction of the outflow of aqueous humor. "Three of them, ROR2, SDCCAG8, and FXYD6, are involved in molecular pathways that might have the slightest relation to glaucoma and are of potential interest for further investigations into their potential roles in glaucoma-related mechanisms." (PMID 34834521, 2021).
Insulin resistance (1 paper, 2019). Increased resistance towards insulin, that is, diminished effectiveness of insulin in reducing blood glucose levels. "WNT inhibitory factor 1 (WIF1), FZD7, and ROR2 are novel biomarkers for the development of insulin resistance." (PMID 30678306, 2019).
ischemic cardiomyopathy (1 paper, 2018). Ischemic cardiomyopathy is a cardiomyopathy in which a weakness in the muscle of the heart due to inadequate oxygen delivery to the myocardium with coronary artery disease being the most common cause. "Interestingly, another ROR family member, ROR2, was downregulated in the ischemic cardiomyopathy samples." (PMID 30342492, 2018).
liver cancer (1 paper, 2024). An epithelial or non-epithelial malignant neoplasm that arises from the liver. "We examined the expression of ROR2 in liver cancer cell lines with different degrees of differentiation using Western blotting." (PMID 37814183, 2024). "Our analysis using liver cancer cell lines showed that ROR2 expression may be related to tumor differentiation in HCC." (PMID 37814183, 2024). "The study examined ROR2 expression in liver cancer cell lines." (PMID 37814183, 2024).
malignant pleural mesothelioma (1 paper, 2024). A malignant neoplasm that arises from mesothelial cells in the pleura and shows a diffuse growth pattern. "Additionally, they examined the expression of ROR1 and ROR2 in human malignant pleural mesothelioma cell lines, finding higher ROR1 expression in H2452 cells than in other human lung mesothelioma cells." (PMID 38791952, 2024).
muscular disease (1 paper, 2024). Myopathy is a peripheral nervous system disease consisting of any abnormal condition or disease of the muscular tissues; commonly designates a disorder involving skeletal muscle. "Finally, our findings indicate that Wnt5b-Ror2 signaling in MPs can serve as a suitable diagnostic and therapeutic target for sarcopenia and various muscular diseases, including DMD." (PMID 39468010, 2024). "It will be of interest to examine how much extents Ror2 signaling, activated synergistically by Wnt5b and Wnt11, will contribute to the progression of muscular diseases accompanied with IMAT accumulation including DMD and sarcopenia." (PMID 39468010, 2024).
myocardial infarction (1 paper, 2020). Gross necrosis of the myocardium, as a result of interruption of the blood supply to the area, as in coronary thrombosis. "In a rat left anterior descending ligation myocardial infarction model, increased protein levels of Wnt5a, Ror2, and Vangl2—one if its immediate downstream targets—were observed in the remote vital area." (PMID 33134326, 2020).
omodysplasia (1 paper, 2014). Omodysplasia is a rare skeletal dysplasia characterized by severe limb shortening and facial dysmorphism. "Omodysplasia is similar to ROR2-related RS, with short limbs and radial dislocation; however, no genital abnormalities are present." (PMID 24932600, 2014).
Peritoneal Fibrosis (1 paper, 2026). Disorder characterized by a wide range of structural changes in PERITONEUM, resulting from fibrogenic or inflammatory processes. "In peritoneal fibrosis, the role of Wnt5a is context dependent: its profibrotic or antifibrotic effects depends on ROR2 expression, with ROR2 silencing reversing the antifibrotic and antiangiogenic activity of Wnt5a." (PMID 41541657, 2026).
silicosis (1 paper, 2021). Silicosis is a respiratory disease caused by breathing in (inhaling) silica dust. "In addition, we identified 2 immune response related genes, ROR2 and SLAMF6, which may play important roles in the pulmonary inflammation that accompanies silicosis." (PMID 34149803, 2021).
Stroke (1 paper, 2025). Sudden impairment of blood flow to a part of the brain due to occlusion or rupture of an artery to the brain. "Upregulation of ADGRL1, CDK5R1/CDKL3, CHRNB2, and ROR2 genes in post-stroke long-lasting brain fatigue generally supports neuroplasticity, cognitive recovery, and neurogenesis, which are beneficial for rehabilitation." (PMID 40006074, 2025). "The upregulation of ADGRL1, CDK5R1/CDKL3, CHRNB2, and ROR2 gene expression in the context of long-lasting post-stroke brain fatigue can have a mix of positive and negative effects, depending on how these proteins influence brain function, recovery, and energy regulation." (PMID 40006074, 2025).
T cell lymphomas (1 paper, 2022). "Further supporting our ALK- ALCL histology data, increased ROR2 expression was recurrently found in other independent ALK- ALCL patient samples and in a few other T cell lymphomas." (PMID 35246138, 2022). "Reanalysis of published ROR2 expression datasets (GSE6338, GSE14879, GSE19069 and GSE65823)) displayed higher ROR2 expression levels in ALK+ ALCL samples compared with other peripheral T-cell lymphoma samples." (PMID 35246138, 2022).
Umbilical hernia (1 paper, 2021). Protrusion of abdominal contents through a defect in the abdominal wall musculature around the umbilicus. "Vertebral segmentation defects and ribs fusion occur in the recessive form linked to ROR2 mutations (MIM# 268310) whereas umbilical hernia and supernumerary teeth are more common in the autosomal dominant forms due to WNT5A (MIM# 180700), DVL1 (MIM# 616331), DVL3 (MIM# 616894) mutations." (PMID 35096710, 2021).
ventricular septal defect (1 paper, 2023). The presence of a defect (opening) in the septum that separates the two ventricles of the heart. "In support of this study, previous researchers found that ventricular septal defects were found to be associated with ROR2‐deficient mice." (PMID 37749917, 2023).